IL6 (interleukin 6)
Diseases named in the same sentence as IL6 in open-access papers (continued):
Sharing a sentence is not in itself a finding about the gene and the disease.
Arthritis (continued). "Arthritis symptoms were improved in mice with collagen-induced arthritis when administered daptomycin, and the serum levels of IL-1β, TNF-α, and IL-6 were decreased." (PMID 41226564, 2025). "Clinically, it has been demonstrated to lower serum uric acid, regulate serum IL-6, TNF-α, and erythrocyte sedimentation rate, and alleviate arthritis induced by HUA." (PMID 41024187, 2025). "Two well-established factors in the etiopathogenesis of arthritis are tumor necrosis factor-alpha (TNF-α) and interleukin-6 (IL-6), two key pro-inflammatory cytokines involved in immune-mediated diseases." (PMID 40289148, 2025). "CRP, an acute-phase protein primarily induced by interleukin-6 (IL-6) during inflammation, typically remains below 60 mg/L in active SLE (except situations of serositis, arthritis, or myositis) but is higher in active versus inactive SLE." (PMID 40988967, 2025). "In CIA-induced arthritis, cartilage destruction and bone erosion were reduced by decreased protein levels of TNF-α, IL-1β, IL-6, iNOS, COX2, MMP-1, and MMP-3 in ankle joint tissue." (PMID 40725063, 2025). "In WT arthritis mice, the serum contents of TNF‐α and IL‐6 decreased with CEL treatment; the IGF2BP3 KO group and the IGF2BP3 KO plus CEL group presented the same trend." (PMID 41164801, 2025). "At the same time, antibiotic treatment worsened arthritis in CIA mice and increased levels of pro-inflammatory cytokines such as interleukin (IL)-6, interferon (IFN)-gamma and IL-17." (PMID 39766360, 2024). "MOIG treatment inhibited the production of IL-1β, IL-6, IL-8 and TNF-α, and reduced the matrix degradation enzymes expressions of MMP2 and MMP3 in TNF-α-stimulated FLSs, thereby blocking the spread of arthritis to distant joints." (PMID 39444614, 2024). "For example, targeting IL-6 with a neutralizing monoclonal antibody (Mab-IL-6.8) has been shown to completely abolish JAK/STAT signaling and alleviate symptoms of arthritis in a primate model." (PMID 38913050, 2024). "In the present study, levels of the representative pro-inflammatory Th1/Th17 cytokines (Il-1b, Tnf-a, Il-6, and Il-17a) in a CIA arthritis model were increased by CIA and reversed by CpdA in an Ffa4 gene-dependent manner." (PMID 38892051, 2024). "CFA-induced arthritis significantly upregulated the serum levels of cytokines, including TNF-α and IL-6, accompanied by an elevation in circulatory inflammatory cells, which can be confirmed through the increased weight of the thymus and spleen." (PMID 39741627, 2024). "Interleukin-6 (IL-6), tumour necrosis factor-alpha (TNF-α), and myeloperoxidase (MPO) play crucial roles in the pathology of various diseases, particularly arthritis and autoimmune conditions." (PMID 39125536, 2024). "The molecular docking results shed light on the potential binding affinities of these compounds with key inflammatory targets involved in arthritis, specifically TNF-α and IL-6." (PMID 38817355, 2024). "IL‐6, IL‐1β, and TNF‐α cytokine levels, on the other hand, significantly increased in the ankle joint tissue when arthritis was induced in mice (model group) (p < .05)." (PMID 39479687, 2024). "Antibodies targeting IL-19 have prevented arthritis and osteolysis in animal models by diminishing the secretion of pro-inflammatory cytokines, including TNF-α, IL-1β, IL-6, and RANKL." (PMID 39104791, 2024). "Severe arthritis predominant: MTX and GC combination therapy, GC and IL-6 blockade combination therapy; IL-1 blockade and GC combination therapy; or IL-1 blockade monotherapy." (PMID 37669122, 2024). "Recent research indicates that buckwheat flavonoids regulate the expression of pro-inflammatory factors (e.g., IL-6, TNF-α), suppress inflammatory responses, and offer therapeutic potential for conditions such as arthritis and cardiovascular disorders." (PMID 39767010, 2024). "Arthritis-related inflammation generates pro-inflammatory cytokines such as TNF-α, IL-6, and interleukin (IL)-1β." (PMID 39458926, 2024).
Arthritis (continued). "In this model, osteostatin reduced the local production of the pro-inflammatory cytokines IL-1β, IL-6, IL-17, and TNF-α, which are increased in patients with arthritis and enhanced the release of the anti-inflammatory cytokine IL-10." (PMID 38474000, 2024). "ELISA detection showed that three doses of WFR can alleviate arthritis in CIA rats in a dose-dependent manner by downregulating abnormally elevated levels of IL-1β, IL-6, and TNF-α (p < 0.01)." (PMID 38098062, 2023). "As a result of blood inflammatory cytokine analysis using an ELISA kit, it was confirmed that the expression levels of TNF-α, IL-6, PGE2, MMP-2, and NO were significantly increased in the serum of mice with arthritis induced by MIA." (PMID 37623223, 2023). "Multiple studies confirmed that LMT-28 reduced gp130 in the IL-6 pathway, phosphorylation of STAT3 with ERK to block signaling, and inhibited of Th17 differentiation, thereby improving arthritis symptoms in CIA, and had a combined effect with metformin." (PMID 37859999, 2023). "RANKL secretion by FLSs is stimulated by IL-1, IL-6, and TNFα produced by macrophages, creating the macrophage–FLS–osteoclast axis for the RANKL-stimulated osteoclastogenesis in arthritis." (PMID 37569682, 2023). "Consistent with the decreases in arthritis score by TAS5315, TAS5315 markedly decreased the levels of TNF-α, IL-1β, and IL-6." (PMID 36821545, 2023). "In arthritis animals, when CD25loFoxp3+T cells lose FOXP3 expression and start to transform into TH17 cells, inflammation stimulates IL-6 produced by synovial cells." (PMID 37064239, 2023). "At the molecular level, CC plays a critical role in the treatment of arthritis by regulating NF-κB, Wnt1/β-catenin and PI3K/AKT/mTOR signaling pathway, inhibiting the expression of IL-6, IL-1β, MMP-3 and TNF-α." (PMID 37637408, 2023). "The administration of PeaNoc XL as an adjunct to standard therapy resulted in a significant reduction in levels of TNF-α (P<0.01), IL-1β (P<0.001), IL-6 (P<0.01), and CRP (P<0.01) in arthritis patients experiencing joint pain and inflammation." (PMID 37767025, 2023). "TNF-α, IL-6, and IL-1 β production were all tempered expressively in CFA-induced arthritis rats given fustin in our study." (PMID 37520245, 2023). "Interleukin-10 (IL-10), IL-1β, mitogen-activated protein kinase (MAPK), IL-6, matrix metalloproteinase-3 (MMP-3), TNF-α and other targets have been confirmed to play important roles in the treatment of arthritis by CC." (PMID 37637408, 2023). "The pathogenesis of CFA-induced arthritis includes the release of inflammatory cytokines, such as TNF-α, IL-1, IL-6, prostaglandins, and serotonins, that migrate to the affected area and lead to edema in particular tissues, such as joint capsule and ligaments." (PMID 37305547, 2023). "The levels of IL-4, IL-6, MCP-1, and TGF-β successively increase with the progression of joint inflammation." (PMID 37256145, 2023). "We also observed a concomitant increase in the levels of many cytokines, including IL-1β, IL-6, TNF-α, and IL-1α, in knee homogenates in WT mice after arthritis induction." (PMID 35439173, 2022). "Pro-inflammatory markers TNF-α, NF-κB, IL-6, IL-1β, and COX-2 were significantly downregulated with piroxicam, EEJR, and NHJR in comparison with the arthritis group." (PMID 35422870, 2022). "In collagen II-induced arthritis male DBA/1J mice, ginkgolide B (10, 20, and 40 μM, i.p., for 43 days) decreased the serum levels of IL-1β, IL-6, TNF-α, MMP-3, and MMP-13 and increased the anti-inflammatory cytokine IL-10." (PMID 35368757, 2022). "Arthritis is an autoimmune disease characterized by chronic, low-grade inflammation, accompanied by increased inflammatory cytokines (i.e., IL-1β, TNF-α, and IL-6)." (PMID 35280697, 2022). "Arthritis induction led to high levels of IL-1β, CXCL1 (chemokine (C–X–C motif) ligand 1), IL-6, TNF-α, and VEGF, which were markedly decreased after BPI treatment three-, two-, two-, 15-, and threefold, respectively." (PMID 36361854, 2022).
Arthritis (continued). "We detected systemic production of TNF-α and IL-6 in the sera of 6-wk-old DNase II−/−Ifnar1−/− and DNase II−/−STINGS365A/S365A mice before the development of arthritis." (PMID 34901991, 2022). "Phlomisoside F (5, 10, and 20 mg/kg, p.o., for 28 days) inhibited the expression of TNF-α, IL-1β, IL-6, COX-2, and 5-lipoxygenase (5-LOX), and increased the expression of IL-10 in complete Freund's adjuvant-induced arthritis male Wistar rats." (PMID 35368757, 2022). "Andrographolide treated CFA-induced arthritis by inhibiting the expression of a series of arthritis-related molecules, including COX-2, NF-κB, p-p38, CD40, TNF-α, IL-1β, and IL-6." (PMID 36238575, 2022). "Aortic vascular mRNA expressions of IL-6 and CXCL-1 were positively correlated while ICAM-1 and VCAM-1 negatively correlated with arthritis score and with radiographic score." (PMID 35488311, 2022). "Panel D-F, both SAP (the murine counterpart of CRP), IL-6 and TNF-α were significantly elevated after induction of arthritis." (PMID 35077491, 2022). "ApoB was reported to aggravate arthritis by eliciting the production of TNF-α, IL-1β, and IL-6 through p38 mitogen-activated protein kinase and NF-κB pathways." (PMID 34996506, 2022). "Andrographolide significantly lowered the levels of proinflammatory cytokines (TNF-α, IFN-γ, IL-6, and IL-17A) in the plasma of mice with complete Freund’s adjuvant (CFA)-induced arthritis while improving the levels of the anti-inflammatory cytokine IL-10." (PMID 36238575, 2022). "When treating complete Freund’s adjuvant-induced arthritis, AG inhibits a series of molecules related to arthritis, such as cyclooxygenase-2 (COX-2), NF-κB, p-p38, CD40, TNF-α, IL-1β, and IL-6." (PMID 36188549, 2022). "In particular, IL-6, TNF-α, IL-1β, and IL-8 play a key role in the pathogenesis and development of arthritis, and high levels of these cytokines have been detected in both the serum and the SF of RA, gout, and CPPD patients." (PMID 36361854, 2022). "These mice developed less incidence of arthritis, decreased clinical arthritis scores, synovitis and had less pro-inflammatory synovial cytokines levels (TNF, IL-1β, IL-6)." (PMID 35455985, 2022). "PQQ has anti-inflammatory effects and can reduce arthritis by inhibiting the production of pro-inflammatory cytokines such as TNF-α and IL-6." (PMID 35592257, 2022). "Treatment of arthritis in mice with antibodies against these proinflammatory cytokines TNF-α and IL-6 has been shown to attenuate the disease." (PMID 35924250, 2022). "Several studies have reported that C-reactive protein (CRP), leukotriene B4 (LTB4), prostaglandin E2 (PGE2), interleukin 6 (IL-6), and tumor necrosis factor-alpha (TNF-α) play crucial roles in inflammatory processes and the pathophysiology of arthritis." (PMID 36046031, 2022). "In a supplemental study, DTHA-mice were euthanized throughout 14 days after induction of arthritis, and blood was analysed for important markers and mediators of RA (SAP, TNF-α and IL-6)." (PMID 35077491, 2022). "For example, in the CIA mouse model and RA patients, the HDAC6 selective inhibitor, CKD-L, inhibits IL-6, TNF-α, and IL-1β expression, and increases IL-10 production, resulting in a decreased arthritis score and inhibited proliferation of effector T cells." (PMID 35453416, 2022). "The main cytokines involved in the inflammatory cascade of arthritis are tumour necrosis factor-α (TNF-α), interleukin (IL)-6, and IL-1." (PMID 33478498, 2021). "It has been reported that IL-6, related to ZFP90, can promote arthritis and joint deformation in SLE cases." (PMID 33796098, 2021). "In a serum‐transfer murine model of arthritis, pro‐inflammatory cytkoines including TNF‐α and IL‐6 are present in the joint." (PMID 32955748, 2021). "IL-6 is also elevated and known to be related to some clinical features of AOSD such as fever, arthritis, and increased production of acute-phase proteins." (PMID 33652679, 2021).
Arthritis (continued). "The WT, Faslpr/lpr, and Fas–/– mice developed autoantibody-induced arthritis (AIA), whereas the Faslgld/gld mice exhibited attenuation of joint swelling and expression of Il6, Tnfa, Il1b, Ccl2, and Ccl3." (PMID 34223817, 2021). "Research confirms that IL-6 has a pivotal role for STAT3 activation in CD4+ T cells, especially for pathogenesis of ACPA-negative arthritis." (PMID 33515210, 2021). "Results showed that kurarinone treatment reduced arthritis severity of CIA mice, as well as their levels of proinflammatory cytokines, TNF-α, IL-6, IFN-γ, and IL-17A, in the serum and paw tissues." (PMID 33924467, 2021). "IL-6 inhibition ameliorated joint swelling, accompanied by remarkably reduced plasma CRP levels when HZ-0408b was administrated after the onset of arthritis in the monkey CIA model." (PMID 35126375, 2021). "The activities of proinflammatory cytokines interleukin 1 beta (IL-1β), IL-6 and tumor necrosis factor alpha (TNF-α) contribute to the pathogenesis of arthritis by promoting proteolytic enzyme activity that damages the cartilage extracellular matrix." (PMID 34198264, 2021). "TQ (5 mg/kg body weight) significantly downregulated the level of pro-inflammatory mediators (IL-1b, IL-6, TNF-α, and prostaglandin E2) to reduce arthritis scoring and bone leaching in collagen-induced arthritis in a Wistar rats in vivo model." (PMID 34067322, 2021). "In the murine collagen type II-induced arthritis model, it was found that LBP decreased the expression of inflammatory mediators TNF-α, IL-6 and IL-17 in a dose-dependent manner." (PMID 34404395, 2021). "In particular, inhibition of IL1, IL-6, and TNF have been reported to be highly effective in suppressing arthritis." (PMID 35008766, 2021). "In a mouse arthritis model, FSTL-1 significantly reduced the expression of IL-6 and MMP-13, thereby reducing joint destruction and synovial inflammation." (PMID 33936382, 2021). "HSP72 expression has been shown to exhibit increased levels in collagen-induced arthritis mouse model and recombinant HSP72 which markedly inhibits the expression of IL-6, TNF-α and NF-κB, highlighting its protective role in arthritis." (PMID 34053448, 2021). "Studies have been carried out on murine models of complete Freund’s adjuvant (CFA)–induced arthritis and SFN administration and showed increased levels of IL-6 and activation of thioredoxin reductase." (PMID 33515210, 2021). "RA is an inflammatory disease, and the inflammatory markers are highly expressed in synovial fluid and serum of patients with arthritis, such as C-reactive protein (CRP: an acute-phase protein), interleukin-6 (IL-6), and tumor necrosis factor (TNF-α)." (PMID 34136020, 2021). "IL-1β, IL-6, and TNF-α are well-known pro-inflammatory cytokines involved in arthritis pathogenesis." (PMID 34451873, 2021). "The pharmacological study on madecassoside demonstrated that it can effectively lessen the related inflammatory factors in arthritis model rats (TNF-α ↓, IL-1b ↓, IL-6 ↓, IFN-γ ↓, IL-17 ↓)." (PMID 33013406, 2020). "Serum IL-6, TNF-α, and IL-17 levels were higher in the arthritis group than the control group (P ˂ 0.001 for all three)." (PMID 32659877, 2020). "Previous studies have suggested that isorhamnetin attenuates collagen-induced arthritis via modulating the levels of cytokines TNF-α, IL-1β, and IL-6 etc. in the joint tissue homogenate of mice." (PMID 32754034, 2020). "Also, increases in IL-6 with an anti-inflammatory characteristic have been the target of encouraging studies involving a possible therapeutic effect of IL-6 in chronic diseases that establish a chronic environment of low-grade inflammation, such as arthritis rheumatoid, sarcopenia and even cancer." (PMID 33178046, 2020). "After administration, the levels of IL-6, IL-1β, and TNF-α decreased, and the arthritis detumescence percentages increased significantly, and the bony erosion degree was distinctly decreased in the TP-CMCS groups and TP group." (PMID 32110979, 2020).
Arthritis (continued). "TGs, which derived from botanical materials, exhibits immune-suppressive functions, and also attenuates inflammation and arthritis through reducing PGE2 production and levels of IL-1α, IL-1β, TNF-α and IL-6." (PMID 32503513, 2020). "In summary, stimulation with TNFα, IL‐6 and MIF lead to cytokine-mediated cartilage degradation, a key feature of arthritis." (PMID 33374446, 2020). "These herbs diminish the expression of inflammatory mediators, such as IL-1, IL-6, TNF-α, PGE2, and COX-2, via modulation of NF-κB activation and kinase activity in in vitro and in vivo arthritis models." (PMID 33126603, 2020). "Higher cardiovascular risk in patients with PsA can also be attributed to the combination of skin and joint inflammation, releasing higher amounts of pro-inflammatory cytokines, such as tumor necrosis factor (TNF)-α, interleukin (IL)-6, IL-17 and IL-23." (PMID 32028959, 2020). "As a result, in experimental arthritis model, MG treatment decreases the levels of cytokines such as TNF-α, IL-6, and IL-17." (PMID 32659877, 2020). "TNF-α, IL-17, IL-6, and DKK-1 serum levels were increased, and obestatin and sclerostin serum levels were decreased in the arthritis group compared to the control group." (PMID 32659877, 2020). "The pro-inflammatory cytokines interleukin-1 (IL-1), IL-6, and TNF-α are heavily involved in the etiology of arthritis." (PMID 30691120, 2019). "The anti-arthritis mechanism of action for ASHW was established through the suppression of pro-inflammatory cytokines such as IL-1β, IL-6, TNF-α; and upstream regulator, NF-κB." (PMID 31142786, 2019). "Various inflammatory mediators are responsible for arthritis and articular deformity, such as TNF-α, IL-6, and IL-17." (PMID 31772500, 2019). "Specific inhibition of IL-6 by a neutralizing monoclonal antibody (Mab-IL-6.8) completely abolished JAK/STAT signaling and relieved symptoms of arthritis in a primate model (Olokizumab)." (PMID 31789602, 2019). "Rats treated with UP1306 showed statistically significant improvements in arthritis severity markers, including uCTX-II (91.4% vs. collagen-induced arthritis (CIA)), serum IL-1β, TNF-α, and IL-6 levels as well as synovial MMP-13." (PMID 30691120, 2019). "Il6−/− SKG mice, which were impaired in T cell differentiation into Th17 cells, hardly developed arthritis." (PMID 31497022, 2019). "We found that expression levels of IL-1β, IL-6, TNFα, CCL3 and MCP-1 molecules were significantly (p < 0.05) increased after induction of arthritis in the bone marrow of KLF2+/− mice compared to KLF2+/+ mice." (PMID 31426355, 2019). "In the present study, we have demonstrated for the first time that IL-6 signal blockade with MR16–1 significantly reduces the development of synovitis and joint destruction in the murine experimental model of spontaneous arthritis and enthesitis, McH/lpr-RA1." (PMID 31200688, 2019). "IL-18Rα KO mice showed lower arthritis and histological scores in bone erosion and synovitis due to reductions in the infiltration of CD4+ T cells and F4/80+ cells and decreased serum IL-6, -18, TNF, and IFN-γ levels." (PMID 31861496, 2019). "We present our findings on RANKL and WNT5A function in osteoclastogenesis and study the effect of the anti-gp130 antibody on RANKL and WNT5A in IL-6–stimulated RA FLS in vitro and in a collagen antibody–induced arthritis (CAIA) mouse model." (PMID 29755657, 2018). "Ermittelt wurden der Arthritis-Score sowie die Serumspiegel von Tumornekrosefaktor-alpha (TNF-α), IL-6 und C‐reaktivem Protein (CRP) anhand der Messung mittels ELISA-Test („enzyme-linked immunosorbent assay“)." (PMID 27900440, 2018). "M10 ameliorated arthritis in the CAIA model, and inhibited RANKL, WNT5A, and Bcl-2 expression in RA FLS by blocking IL-6 signaling, likely via Janus kinase–STAT3 pathway downregulation." (PMID 29755657, 2018). "We assessed arthritis score; production of TNF-α, IL-6, and CRP in serum; and histological changes of ankle joints." (PMID 27900440, 2018).